QPRT (quinolinate phosphoribosyltransferase)
Description:
Involved in the catabolism of quinolinic acid (QA).
Synonyms: QPRTase; HEL-S-90n
Tractability: Small molecule: a structure with a bound ligand is known; it has a binding pocket of medium quality. PROTAC: ubiquitination databases record sites on it; its protein half-life has been measured.
Gene: Protein-coding gene on chromosome 16 (29,663,279 to 29,698,704, forward strand). Ensembl gene ENSG00000103485.
Subcellular location (Human Protein Atlas): Vesicles
Pathways (Reactome):
Metabolism: Nicotinate metabolism
Gene Ontology:
Molecular function: identical protein binding; nicotinate-nucleotide diphosphorylase (carboxylating) activity; protein binding; pentosyltransferase activity
Biological process: quinolinate catabolic process; 'de novo' NAD+ biosynthetic process from L-tryptophan; NAD+ biosynthetic process
Cellular component: catalytic complex; extracellular exosome; cytosol
Genetic constraint (gnomAD): Loss-of-function variants: 16 observed, 19.89 expected, observed/expected ratio (o/e) 0.8, 90% interval 0.54 to 1.22. The upper end of that interval is the gene's LOEUF score, 1.22, which puts it in group 5 of 6, group 1 being the genes least tolerant of losing a copy. Missense variants: 324 observed, 380.42 expected, observed/expected ratio (o/e) 0.85, 90% interval 0.78 to 0.93. Synonymous variants: 173 observed, 183.73 expected, observed/expected ratio (o/e) 0.94, 90% interval 0.83 to 1.07.
Homologues: Orthologues: chimpanzee QPRT (99% identical), macaque QPRT (97% identical), dog QPRT (86% identical), pig QPRT (85% identical), rabbit QPRT (84% identical), mouse Qprt (83% identical), guinea pig QPRT (82% identical), rat Qprt (81% identical), tropical clawed frog qprt (52% identical).
Diseases named in the same sentence as QPRT in open-access papers:
QPRT is named in the same sentence as 47 diseases in open-access papers, as found by Europe PMC text mining. Sharing a sentence is not in itself a finding about the gene and the disease. The quoted sentences say what the papers report.
breast carcinoma (8 papers, 2020 to 2025). "In this study, we provided strong evidence supporting the association between QPRT upregulation and tumor progression in breast cancer." (PMID 33613454, 2020). "Recently, QPRT was identified as a crucial prognostic gene that was significantly associated with breast cancer overall survival." (PMID 33613454, 2020). "Taken together, the results suggest that the QPRT protein expression in breast neoplasms was associated with the aggressiveness of breast cancer." (PMID 33613454, 2020). "Interestingly, QPRT has been reported to be highly expressed in breast cancer and is associated with high tumor aggressiveness and poor patient outcomes." (PMID 40611146, 2025). "We reasonably believe that QPRT is likely to interact with these genes or proteins and affect the progression of breast cancer." (PMID 37723185, 2023). "Multiple genes or proteins interact with QPRT in different ways and participate in the occurrence, development, invasion, and metastasis of breast cancer, but few have been verified." (PMID 37723185, 2023). "Collectively, our results here support a vital role for QPRT in breast cancer and indicate that its upregulation is related to the poor prognosis of patients with BRCA." (PMID 35251175, 2022). "Upregulated QPRT expression is an independent predictor of breast cancer prognosis and promotes breast cancer progression by activating the PI3K/Akt signalling pathway." (PMID 35251175, 2022). "Among them, the expression of QPRT has a prominent effect on the prognosis of breast cancer patients." (PMID 35251175, 2022). "QPRT overexpression in breast cancer was further validated in spontaneous mammary tumors from MMTV-PyVT transgenic mice." (PMID 33613454, 2020). "both showed that QPRT positively participates in regulating the migratory and invasive capacity of breast cancer cells." (PMID 33613454, 2020). "In this study, we aimed to explore the clinicopathological significance of QPRT expression in breast cancer and its potential biological mechanisms." (PMID 33613454, 2020). "Consistently, ectopic expression of QPRT promoted cell migration and invasion in breast cancer cells." (PMID 33613454, 2020). "QPRT promotes cell migration and invasion of breast cancer cells through, at least in part, the phosphorylation of myosin light chain via Rho GTPase and PLC pathways downstream of purinergic receptors." (PMID 33613454, 2020). "While normal mammary gland tissues from wild-type mice exhibited virtually undetectable QPRT expression, mammary tumors of MMTV-PyVT mice had relatively abundant QPRT protein expression." (PMID 33613454, 2020). "In this study, we demonstrated that QPRT expression was upregulated in invasive breast cancer and spontaneous mammary tumors from MMTV-PyVT transgenic mice." (PMID 33613454, 2020). "Second, spontaneous mammary tumors from MMTV-PyVT transgenic mice showed a similar trend of QPRT overexpression." (PMID 33613454, 2020). "Lastly, high expression levels of QPRT, the rate-limiting enzyme that converts QA to NAMN, enhance the migration and invasive properties of breast cancer cells and are associated with worsened prognoses and clinical outcomes in breast cancer patients." (PMID 38396769, 2024). "Similarly, we found that the expression level of QPRT in breast cancer tissues was significantly higher than that in normal tissues." (PMID 37723185, 2023). "QPRT may influence the occurrence and progression of breast cancer through the PI3K-AKT signalling pathway, Wnt signalling pathway, and cell cycle-related molecules." (PMID 37723185, 2023). "It has been shown that QPRT promotes breast cancer progression by activating the PI3K/Akt pathway." (PMID 37723185, 2023). "The results showed that under the effect of QPRT, breast cancer could be regulated by immune cells in development and prognosis." (PMID 37723185, 2023). "In ER+ breast cancer, DSCAM-AS1 increased QPRT expression and caused poor prognosis." (PMID 37723185, 2023).
breast carcinoma (continued). "We speculate that QPRT may play a role in breast cancer through the regulation of the cell cycle and modulation of molecules in the Wnt signalling pathway." (PMID 37723185, 2023). "We hypothesize that QPRT is likely to be directly or indirectly involved in cell cycle regulation and consequently impacts the occurrence and progression of breast cancer." (PMID 37723185, 2023). "Another study found down syndrome cell adhesion molecule antisense RNA 1 (DSCAM-AS1) increases QPRT expression in breast cancer cells via competitively binding miRNA-150-5p and miRNA-2467-3p, resulting in increased cell growth, migration, and invasion of estrogen-receptor breast cancer cells." (PMID 37876966, 2023). "Subsequently, in vitro experimental results show that QPRT upregulation may affect breast cancer progression by activating the PI3K/Akt signalling pathway." (PMID 35251175, 2022). "The current study implies that QPRT may therefore be a novel specific therapeutic target for breast cancer treatment." (PMID 35251175, 2022). "Third, QPRT depletion significantly hindered the invasiveness of breast cancer cells." (PMID 33613454, 2020). "Knockdown of QPRT expression inhibited breast cancer cell migration and invasion." (PMID 33613454, 2020). "Altogether, these results indicate that QPRT enhanced breast cancer invasiveness probably through purinergic signaling and might be a potential prognostic indicator and therapeutic target in breast cancer." (PMID 33613454, 2020). "For example, QPRT, one of the rate-limiting enzymes of NAD+ biosynthesis, was shown to potentially enhance breast cancer invasiveness through purinergic signaling." (PMID 37006438, 2023). "It is possible that the concentration of PA is not sufficient to inhibit the activity of QPRT, as a recent study demonstrated that concentrations > 100 μM were required to inhibit invasion in breast cancer cells overexpressing QPRT." (PMID 38893173, 2024). "The immunohistochemical results showed that QPRT was localized in the cytoplasm, cell membrane, and nucleus and showed a positive expression in pathological breast cancer tissues but not in normal tissues." (PMID 35251175, 2022). "QPRT depletion did not have adverse effects on cell viability or growth in breast cancer cells." (PMID 33613454, 2020). "QPRT overexpression is known to activate the PI3K/Akt signalling pathway in cancer cells, but this has not been proven in breast cancer." (PMID 35251175, 2022).
acute kidney injury (5 papers, 2021 to 2025). Sudden and sustained deterioration of the kidney function characterized by decreased glomerular filtration rate, increased serum creatinine or oliguria. "The biosynthetic routes leading to de novo nicotinamide adenine dinucleotide (NAD+) production are involved in acute kidney injury (AKI), with a critical role for quinolinate phosphoribosyl transferase (QPRT), a bottleneck enzyme of de novo NAD+ biosynthesis." (PMID 34793337, 2022). "Similarly, although minimal, NAD+ biosynthesis from tryptophan, at the expense of the quinolinate phosphoribosyltransferase, also prevents renal NAD+ depletion and mediates resistance to acute kidney injury." (PMID 35173682, 2021). "The reduction of QPRT activity in the kidney was reported to be sufficient to significantly reduce NAD+ levels and sensitize patients to acute kidney injury (AKI)." (PMID 35681770, 2022).
Alzheimer disease (4 papers, 2011 to 2016). A progressive, neurodegenerative disease characterized by loss of function and death of nerve cells in several areas of the brain leading to loss of cognitive function such as memory and language. "The only gene more methylated in CC than in SAC was QPRT which codes for an enzyme that was found to detoxify quinolinate, a potent endogenous neuron toxin that is elevated in the brain of patients with neurodegenerative disorders such as Alzheimer's disease." (PMID 26388956, 2015).
follicular thyroid carcinoma (4 papers, 2009 to 2023). "QPRT, which encodes a key enzyme in the catabolism of quinolinate, an intermediate in the tryptophan-nicotinamide adenine dinucleotide pathway, is a potential marker for follicular thyroid carcinoma including the minimally invasive variant." (PMID 31552180, 2019). "QPRT protein could be detected by immunohistochemistry in 65% of follicular thyroid carcinomas including minimal invasive variant and only 22% of follicular adenomas." (PMID 19321014, 2009). "In addition, other researchers claimed that QPRT protein was observed in follicular thyroid carcinomas by immunohistochemistry techniques with a high ratio, and it could be potentially used as a new marker for follicular thyroid nodule investigations." (PMID 36500178, 2022).
neuroblastoma (3 papers, 2011 to 2018). Neuroblastoma (NB) is the most common solid, extracranial childhood tumor. "In summary, our findings allow us to conclude that in the neuroblastoma model SH-SY5Y a loss of QPRT impairs neuronal development in vitro by changing genetic networks previously implicated in the etiology of ASD." (PMID 30443311, 2018). "QPRT function was inhibited in SH-SY5Y neuroblastoma cells using (i) siRNA knockdown (KD), (ii) chemical mimicking of loss of QPRT, and (iii) complete CRISPR/Cas9-mediated knock out (KO)." (PMID 30443311, 2018).
autism spectrum disorder (2 papers, 2019 to 2021). A spectrum of developmental disorders that includes autism, and Asperger syndrome. "QPRT regulates the genes and gene networks related to neuronal differentiation of SH-SY5Y cells in vitro, suggesting the function of QPRT in the pathogenesis of autism spectrum disorders in Chr16p11.2 deletion carriers." (PMID 34079576, 2021).
glioma (2 papers, 2014 to 2016). A benign or malignant brain and spinal cord tumor that arises from glial cells (astrocytes, oligodendrocytes, ependymal cells). "Our results are partly consistent with these findings showing that both 3-HAAO and QPRT were expressed in all glioma samples constitutively and upon IFN-γ stimulation." (PMID 25415278, 2014). "Importantly, a recent study suggested that QPRT is highly involved in denovo NAD+ synthesis in glioma in which approximately 30% oftumours are derived from the brain and central nervous system and 80% from allmalignant brain tumours." (PMID 26805589, 2016). "QPRT expression was significantly up-regulated in stimulated and unstimulated glioma compared to stimulated and unstimulated HFA, respectively, confirming the NAD+ hypothesis." (PMID 25415278, 2014). "Up-regulation of QPRT expression compared to HFA constitutively and in response to inflammatory stimuli (IFN-γ) may be a mechanism conferring tumor survival advantages, as the glioma may have a greater capacity to produce NAD+ in times of inflammatory stress." (PMID 25415278, 2014).
Hepatitis C infection (2 papers, 2017 to 2021). "Consistent with this view, the enzyme in the last step of the de novo pathway, quinolinate phosphoribosyltransferase (QPRT), is reported to be an antiviral host factor against Hepatitis C infection." (PMID 34871367, 2021).
leukaemia (2 papers, 2018 to 2023). "Different from CEM leukemia cells, they do not rely on QPRT as an alternative NAD+-producing enzyme and NAPRT-mediated NAD+ biosynthesis also seems not be involved in their resistance phenotype." (PMID 29541451, 2018).
melanoma (2 papers, 2008 to 2023). A malignant, usually aggressive tumor composed of atypical, neoplastic melanocytes. "The Kaplan–Meier analysis showed that five upregulated genes were significantly related to both the OS and DFS of melanoma patients, including TUBB4A, PSEN2, SLC45A2, QPRT, and TRPV2." (PMID 37439014, 2023). "Genes such as KRT14, GJA1, S100A7, S100A9, and EHF were higher in most melanomas while genes such as CITED-1, GDF15, QPRT, OCA2, c-MET and MME were more highly expressed in NHEM." (PMID 18442402, 2008).
psoriasis (2 papers, 2021). An autoimmune condition characterized by red, well-delineated plaques with silvery scales that are usually on the extensor surfaces and scalp. "Viceversa, QPRT expression was significantly downregulated in psoriasis lesions at baseline compared to QPRT observed in healthy or NLS groups, and it was restored by secukinumab treatment." (PMID 34202251, 2021).
schizophrenia (2 papers, 2019 to 2021). A major psychotic disorder characterized by abnormalities in the perception or expression of reality. "Studies of kynurenine pathway metabolism among individuals with duplications of 16p11.2, who harbor three copies of the QPRT gene, would be of particular interest given the association of this duplication with elevated rates of schizophrenia." (PMID 31548888, 2019).
acute myeloid leukemia (1 paper, 2022). Acute myeloid leukemia (AML) is a group of neoplasms arising from precursor cells committed to the myeloid cell-line differentiation. "The quinolinate phosphoribosyltransferase (QPRT) gene was shown to be activated by Wilms’ tumor gene 1 (WT1) resulting in expanded antiapoptotic properties in acute myeloid leukemia and acting as an oncogenic protein." (PMID 36500178, 2022).
alopecia (1 paper, 2022). Hair loss usually from the scalp. "Our findings suggest that NNMT and QPRT, which link NAD + expression and activity, may be deemed potential therapeutic targets for alopecia treatment." (PMID 35181715, 2022).
colorectal cancer (1 paper, 2026). A primary or metastatic malignant neoplasm that affects the colon or rectum. "Functional validation demonstrated that ZIC2 overexpression significantly enhanced colorectal cancer cell migration and proliferation, accompanied by upregulation of QPRT." (PMID 41694394, 2026). "ZIC2 may promote the colorectal cancer progression by upregulating QPRT." (PMID 41694394, 2026).
COVID-19 (1 paper, 2023). A disease caused by infection with severe acute respiratory syndrome coronavirus 2. "The huge plasma QA elevation despite the apparent KMO inhibition suggests that host QA metabolism to NAD+ may be inhibited in COVID-19: perhaps by decreased quinolinate phosphoribosyltransferase (QPRT)." (PMID 37486805, 2023).
fibrosarcoma (1 paper, 2018). A malignant mesenchymal fibroblastic neoplasm affecting the soft tissue and bone. "Notably, a dependency on QPRT activity was recently observed in human fibrosarcoma cells with acquired resistant to NAMPT inhibition that still presented a point mutation in the NAMPT enzyme." (PMID 29541451, 2018).
Hypertryptophanemia (1 paper, 2022). "As a gene for protein-coding, diseases related to QPRT (Quinolinate Phosphoribosyltransferase) contain Hypertryptophanemia and Pellagra." (PMID 35345651, 2022).
kidney transplant (1 paper, 2022). A surgical procedure in which one or both kidneys from a donor are implanted into a recipient. "QPRT mRNA levels were significantly reduced in the first hours after ischemia-reperfusion injury (IRI) in protocol biopsies obtained in 42 kidney transplant recipients (KTRs) before and after reperfusion." (PMID 34793337, 2022).
malignant glioma (1 paper, 2025). A grade III or grade IV glioma arising from the central nervous system. "This process is catalyzed by the enzyme quinolinate phosphoribosyltransferase (QPRT), whose elevated levels have been reported in highly malignant gliomas." (PMID 40075568, 2025).
Parkinson disease (1 paper, 2018). A progressive degenerative disorder of the central nervous system characterized by loss of dopamine producing neurons in the substantia nigra and the presence of Lewy bodies in the substantia nigra and locus coeruleus. "Indeed, they reported shorter stride lengths in aged but not middle-aged QPRT-KO mice as usually seen in mouse models of Parkinson’s disease." (PMID 30443311, 2018).
prostate carcinoma (1 paper, 2023). A carcinoma that arises from epithelial cells of the prostate gland. "QPRT affects malignant phenotype in cancer cells and is proposed as an antitumoral gene in prostate cancer which may prevent the progression of the disease." (PMID 37535601, 2023).
renal cell carcinoma (1 paper, 2023). "For example, studies in renal cell carcinoma revealed QPRT to be downregulated in tumors and loss of QPRT expression led to anchorage-independent growth of RCC cells." (PMID 37876966, 2023).
renal fibrosis (1 paper, 2021). A final common manifestation of a wide variety of chronic kidney diseases characterized by glomerulosclerosis and tubulointerstitial fibrosis. "The proteins expressions of renal fibrosis, quinolinate phosphoribosyltransferase (QPRT), sirtuin 3 (SIRT3), and mitochondrial dynamics were determined and quantified by Western blot analysis." (PMID 34938344, 2021).